TLR2 (toll like receptor 2)
Diseases named in the same sentence as TLR2 in open-access papers (continued):
Sharing a sentence is not in itself a finding about the gene and the disease.
cystic fibrosis (20 papers, 2008 to 2024). Autosomal recessive disorder caused by pathogenic variants in the CFTR gene (cystic fibrosis transmembrane conductance regulator), which encodes a chloride and bicarbonate channel expressed in epithelial cells, and follow the diagnosis criteria. "For example, hypomethylation of the gene for the innate immune receptor Toll-like receptor 2 (TLR2) is associated with an increased pro-inflammatory response to bacterial peptidoglycan in bronchial epithelial cells from patients with cystic fibrosis (Ref." (PMID 38557638, 2024). "In the clinical course of cystic fibrosis, dysregulated expression of TLR2 caused chronic inflammation." (PMID 22438967, 2012). "In the clinical course of cystic fibrosis, increased expression of TLR2 caused chronic inflammation." (PMID 22438967, 2012). "In addition, promoter hypomethylation of the Toll-like receptor-2 gene was associated with increased proinflammatory response toward PGN in cystic fibrosis bronchial epithelial cells." (PMID 32283626, 2020). "TOM1 is also involved in the Toll-like receptors 2/4 (TLR2/4) signaling pathways in cystic fibrosis, an inherited disorder characterized by chronic airway inflammation." (PMID 33718385, 2021). "miR-126 controls TLR2/4 inflammatory signaling pathways by modulating TOM1 expression in cystic fibrosis lung." (PMID 25070658, 2014). "PGN could induce more severe inflammatory responses, when promoter methylation of TLR-2 gene was decreased in cystic fibrosis bronchial epithelial cells." (PMID 32545333, 2020). "Furthermore, increased availability of TLR2 in epithelial cells corresponded to an increase in proinflammatory responses seen in the airways of cystic fibrosis patients." (PMID 33013394, 2020). "TLR2 stimulation may alter the expression of TLR5 as expression of TLR5 is upregulated in neutrophils from patients with cystic fibrosis in response to TLR2 stimulation." (PMID 31774834, 2019). "However, Sp1 has been shown to act as a critical component of the DNA demethylation-dependent upregulation of TLR2 expression in cystic fibrosis epithelial cells." (PMID 26223836, 2015). "Cystic fibrosis patients are prone to infection since absence of CFTR protein causes demethylation of DNA at the specific CpG sites which overlaps a minimal region to maintain activity of TLR2 promoter." (PMID 33879218, 2021). "Similarly, another Prevotella species induced TLR2 signaling but fewer pro-inflammatory cytokines than a cystic fibrosis pathogen in human CF bronchial epithelial cells." (PMID 35680890, 2022). "Thus, in addition to the regulation of IL-1R1 surface expression, the TOM1-TOLLIP complex may also modulate TLR2/4 recycling by employing a similar mechanism, thereby having an anti-inflammatory role in cystic fibrosis and possibly in other inflammatory diseases." (PMID 33718385, 2021). "Concerning other TLRs, Mizunoe and colleagues reported that IL-17A enhanced the production of IL-8 induced by peptidoglycan (TLR2 agonist) or lipopolysaccharide (TLR4 agonist) in bronchial epithelial cells from cystic fibrosis patients, but not in NHBE cells." (PMID 26418032, 2015). "We found that, in CF AECs expressing a deletion of a phenylalanine at position 508 of the gene coding for Cystic Fibrosis Transmembrane Conductance Regulator (CFTRdelF508), exposure to live Pseudomonas aeruginosa upregulates IL-33 via the TLR2 and TLR5 signaling pathways." (PMID 26793709, 2015). "In human cystic fibrosis bronchial epithelial cells, curcumin lowers the nuclear expression of transcriptional stimulatory protein 1 (SP1), which is among the critical reasons for the enhanced production of basic TLR2." (PMID 37110167, 2023). "Thus, several publications revealed a contribution of TLR2 or TLR4 in non-infectious acute lung injury (ALI), acute respiratory distress syndrome (ARDS), chronic obstructive pulmonary disease (COPD), cystic fibrosis and asthma." (PMID 28836991, 2017).
Lyme disease (20 papers, 2006 to 2025). Lyme disease (named after the towns in the USA where the disease was first identified) is a bacterial infection caused by Borrelia burgdorferi. "Taken together these results indicate that a functionally deficient TLR2 variant plays opposite roles in two different infectious diseases: protection in the context of Lyme disease and susceptibility in the context of TB." (PMID 22529866, 2012). "The principal proinflammatory DAMPs of the spirochetal pathogen Borrelia burgdorferi, the causative agent of Lyme disease, are triacylated lipoproteins recognized by heterodimers of TLR2 and TLR1." (PMID 20011115, 2009). "Macrophages express CD14 which partners with Toll-like receptor 2/1 to recognize bacterial lipoproteins such as those of Borrelia burgdorferi, the causative agent of Lyme disease." (PMID 20011115, 2009). "To test this hypothesis, we isolated monocyte-derived dendritic cells from healthy subjects, exposed them to the TLR-2 agonist lipoteichoic acid or live Borrelia burgdorferi, the causative agent of Lyme disease, and isolated and characterized HLA-DR associated peptides using mass spectrometry." (PMID 33043033, 2020). "In our initial investigation of TLR1, TLR2, and TLR5 variants in Lyme disease, we found that patients with post-infectious LA had a greater frequency of TLR1-1805GG (62%) compared to patients with antibiotic-responsive LA (47%)." (PMID 41333458, 2025). "Toll-like receptor 2 (TLR2) plays a crucial role in the immune response to the outer-surface lipoprotein A (OspA) of B. burgdorferi, the causative agent of Lyme disease, by recognizing tripalmitoyl-S-glyceryl-cysteine (Pam3Cys)-modified lipoproteins." (PMID 39852815, 2025). "We also looked the presence of T regulatory cells in the joints and hearts of WT and TLR2−/− mice, since these have been suggested to play a role in Lyme disease pathogenesis." (PMID 27857714, 2016). "Recent studies have shown that TLR2 mediates signaling from endosomal vesicles, in addition to the plasma membrane, particularly during Borrelia burgdorferi infection." (PMID 26502905, 2015). "Previous studies showed that γδ T cell activation in response to Borrelia burgdorferi infection in a TLR2-dependent manner, suggesting an involvement of MyD88 signaling during in vivo activation." (PMID 25232836, 2014). "Because an increase in acetyl-CoA metabolism is driven by alterations in intracellular acetate utilization, we believe that this therapy can be used to effectively attenuate the TLR2-induced neural immune response as found in Lyme neuroborreliosis." (PMID 23134838, 2012). "One report observed a lower frequency of TLR2 753Q in Lyme disease patients than healthy controls (OR = 0.39, P = 0.033) and an even stronger protective effect was conferred in late stage Lyme disease patients (OR = 0.16, P = 0.018)." (PMID 22529866, 2012). "Recently, it has been reported that TLR2 on macrophages mediates responses to lipoproteinsof Borrelia burgdorferi, which is an etiologic agent of Lyme disease." (PMID 16864901, 2006). "Increased TLR2 expression in unstimulated neutrophils suggests an important role of these cells in mechanism recognition of Bburgdorferi in patients with Lyme disease." (PMID 16864901, 2006). "Concluding, increased TLR2 expression in neutrophils of patients with Lyme disease indicates an important role of these cells inrecognition of B burgdorferi." (PMID 16864901, 2006). "To test if the anti-inflammatory effect of acetate supplementation is specific to a TLR4-mediated injury, we measured markers of neuroglia activation in rats subjected to B. burgdorferi-induced neuroborreliosis that is mediated in large part by a TLR2-type mechanism." (PMID 23134838, 2012). "TLR2 expression in relation to expression and production of cytokines and their regulators suggestsa role of this receptor in enhanced IL-6- and inhibition of IL-1β-mediated reactions in patients with Lyme disease." (PMID 16864901, 2006).
Lyme disease (continued). "Recently, it has been reported that TLR2 on macrophages plays a unique role in the inflammatory response and host defense to infection withBorrelia burgdorferi (Bb) which is an etiologic agent of Lyme disease." (PMID 16864901, 2006). "The distinct patterns of pro-inflammatory mediator production, along with TLR2/TLR1 expression, and regulation in macrophages from Lyme disease-resistant and -susceptible mice suggests itself as a blueprint to further investigate differential pathogenesis of Lyme disease." (PMID 23024745, 2012). "For example, the TLR2 gene is targeted by Erlotinib (DB00045), which is used to prevent Lyme Disease." (PMID 28817730, 2017). "In the present study, changes in TLR2 expression and cytokine production in freshly isolated PMNand PBMC from patients with Lyme disease before treatment were found." (PMID 16864901, 2006). "However, TLR knockout and overexpression studies have confirmed that lipoproteins drive inflammation in syphilis and Lyme disease through TLR-dependent (TLR1, TLR2) responses." (PMID 25071771, 2014). "Using a mouse model of Lyme disease, we show that B. burgdorferi-activated CD14−/− MΦ release significantly more proinflammatory cytokines and do so in a manner only partially dependent on TLR2." (PMID 20011115, 2009). "In the present study, TLR2 expression in relation to expression and production of IL-1β, IL-6, as well as their natural regulators (sIL-1RII, IL-1Ra and sIL-6Rα, sgp130, resp) production by PMN of peripheral blood in patients with Lyme disease were estimated." (PMID 16864901, 2006). "In the present study, TLR2 expression and productionof IL-1β and IL-6 as well as their natural regulators (sIL-1RII, IL-1Ra and sIL-6Rα, sgp130, resp) by PMN of peripheral blood in patients with Lyme disease were examined." (PMID 16864901, 2006). "Our observed TLR2/TLR1 imbalance/dysregulation is not unique to the mouse model of Lyme disease." (PMID 23024745, 2012). "However, there is no available data about TLR2 expression in PMN of patientswith Lyme disease." (PMID 16864901, 2006). "More broadly, it also demonstrates that, notwithstanding similarities in the exaggerated Lyme disease phenotype observed in CD14−/− and TLR2−/− mice, these two signaling pathways are not entirely synonymous." (PMID 20011115, 2009).
Anxiety (19 papers, 2015 to 2025). Intense feelings of nervousness, tension, or panic often arise in response to interpersonal stresses. "In conclusion, our study demonstrates that minocycline alleviates S. aureus infection-induced neuroinflammation and anxiety-like behaviors by suppressing the TLR2 and STAT3 signaling pathways in microglia." (PMID 40002461, 2025). "Treatment with Tlr2 agonist lipoteichoic acid was found to induce anxiety-related behaviors in mice." (PMID 39905541, 2025). "Increased Tlr2 mRNA expression level was observed in a rat model of chronic unpredictable stress induced anxiety, which was reduced by the administration of the anxiolytic oregano extract." (PMID 39905541, 2025). "For example, TLR2 knockout mice exhibit reduced anxiety, impaired sociability, aggression, and cognitive defects." (PMID 38891900, 2024). "There is also evidence that anxiety and social avoidance are induced by microglial activation through TLR2/4 in a repeated social defeat stress-induced depression model." (PMID 39408923, 2024). "The results demonstrated that TLR2 deficit induced learning disabilities, decreased spontaneous activity, increased anxiety and depression, and led to white matter damage (WMD), brain atrophy, loss of neurons, and glial activation." (PMID 31509519, 2019). "In contrast to our results from TLR-2 KO mice, it has been reported that the Myd88 deficiency in C57BL/6 mice showed more anxiety, better motor coordination, and improved spatial learning than WT mice." (PMID 25687169, 2015). "Next, we conducted an elevated plus-maze test and a marble-burying test to confirm the anxiety-like behavior in TLR-2 KO mice." (PMID 25687169, 2015). "TLR-2 KO mice showed a marked increase in the number of crossings in the anxiety-provoking center of the open field compared to WT mice." (PMID 25687169, 2015). "Collectively, these results indicate that TLR-2 KO mice show hyperlocomotion and reduced anxiety-like behaviors in a novel environment." (PMID 25687169, 2015). "Similarly, higher TLR2 expression was observed in patients diagnosed with bipolar disorder and anxiety and on Th17/Tc17-like cells in MDD patients with comorbid multiple sclerosis." (PMID 40558558, 2025). "However, minocycline’s effects in terms of ameliorating S. aureus infection-induced TLR2-dependent microglia activation and anxiety-like behaviors are still unclear." (PMID 40002461, 2025). "Notably, the loss of TLR2/4 abolished R-SDS-induced social avoidance and anxiety in mice while mitigating stress-induced neuronal response attenuation, dendritic atrophy, and microglial activation in the mPFC." (PMID 40558558, 2025). "Similarly, in a rat model of chronic unpredictable stress, TLR2 gene expression levels decreased in parallel with improvements in anxiety-like behavior and cognitive dysfunction in treated rats." (PMID 40558558, 2025). "Furthermore, it has been revealed that TLR2 and TLR4‐associated signaling pathways are involved in cognitive dysfunction and anxiety behavior by inducing neuroinflammation." (PMID 35898162, 2022). "The importance of the immune system in generating anxiety symptoms resulting from alcohol withdrawal is demonstrated by the fact that elimination of TLR4 and/or TLR2 in mice inhibited the production of inflammatory mediators in the striatum and prevented the onset of anxiety symptoms." (PMID 35095609, 2021). "The TLR2-/- mice we tested showed increased baseline anxiety-like behavior." (PMID 31404078, 2019). "TLR4 and TLR2 knockout mice are protected from chronic ethanol (5 weeks) induction of striatal and serum cytokines/chemokines, autophagy impairments, glial activation, NFκB activation, cortical caspase-3 activation, anxiety-like behavior, and working memory deficits." (PMID 33806288, 2021). "However, the absence of TLR2 in mice is associated with increased anxiety levels." (PMID 40558558, 2025).
Anxiety (continued). "It was shown that deletion of TLR2 and TLR4 eliminated repeated social defeat stress (R-SDS)-induced social avoidance and anxiety in mice." (PMID 41459223, 2025). "TLR2 and TLR4 have been identified as crucial mediators in generating neuroinflammation, leading to neuronal changes and anxiety behavior." (PMID 35898162, 2022). "Different molecular signaling pathways, such as BDNF, TrkB, TLR2, and TLR4, are involved in the pathogenesis of anxiety and cognitive decline." (PMID 35898162, 2022). "For instance, the toll-like receptor 2/4 (TLR2/4) has been reported to mediate stress-induced microglial activation in the prefrontal cortex, which subsequently induces the development of anxiety-like behaviors in animals." (PMID 34996472, 2022). "Therefore, in our study, the higher anxiety levels observed in the TLR2-/- mice in the hole-board test might have heightened their freezing behavior in the contextual conditioned situation rather than enhancing the hippocampus-dependent memory processes per se." (PMID 31404078, 2019). "Moreover, high-fat diet fed mice display decreased TLR2 and increased TLR4 mRNA expression in the hippocampal tissue and anxiety- and depressive-like behaviors compared to lean-fed mice." (PMID 40558558, 2025). "TLR2/4 is a key mediator of R-SDS-induced activation of microglia in the mPFC, leading to anxiety." (PMID 41459223, 2025). "In this study, we found that peripheral injury of the trigeminal nerve following dIoN-CCI surgery induced trigeminal neuropathic pain and anxiety-like behavior in mice, triggering microglia activation in the ipsilateral TNC, with the up-regulation of microglia TLR2 expression in the TNC." (PMID 34000998, 2021). "In addition to hyperlocomotion, TLR-2 KO mice showed reduced anxiety-like behaviors, but not a depression-like behavior." (PMID 25687169, 2015). "Several mechanisms involved in spike protein have been proposed at the mice level such as TLR2-mediated depression, TLR4-mediated cognitive dysfunction, and anxiety mediated by non-cell autonomous hippocampal neuronal cell deaths by inducing IL-1β from glial cells." (PMID 38834668, 2024).